RN7SL266P (RNA, 7SL, cytoplasmic 266, pseudogene)
Gene: Miscellaneous RNA gene on chromosome X (112,855,874 to 112,856,162, forward strand). Ensembl gene ENSG00000243011.
Homologues: Orthologues: chimpanzee Metazoa_SRP (100% identical), macaque Metazoa_SRP (95% identical). Paralogues in human: RN7SL1 (79% identical), RN7SL2 (79% identical), RN7SL3 (78% identical), RN7SL566P (77% identical), RN7SL712P (77% identical), RN7SL296P (76% identical), RN7SL342P (76% identical), RN7SL147P (76% identical), RN7SL518P (76% identical), RN7SL113P (75% identical), RN7SL220P (75% identical), RN7SL395P (75% identical), and 701 more.